GPX3 (glutathione peroxidase 3)
Diseases named in the same sentence as GPX3 in open-access papers (continued):
Sharing a sentence is not in itself a finding about the gene and the disease.
tumor (continued). "We hypothesize that GPX3 exhibits a tumor suppressive effect during the transition from normal epithelial mucosa to early GC." (PMID 37790850, 2023). "Similarly, after their culture with ECs, IL30-overexpressing PCs showed a dramatic upregulation of a wide range of oncogenes, which included CCND2, EGR3, IGFBP5, KLK3, PDLIM4, PTGS1 and SHBG and a few tumor suppressors, such as GPX3, FOXO1, MAX and NKX3-1." (PMID 38087324, 2023). "Aside from that, GPX3 may contribute to cancer via increasing tumor immune cell infiltration, enhancing immune checkpoint expression, and reducing the sensitivity to chemotherapy drugs." (PMID 37790850, 2023). "Further experiments are needed to verify how GPX3 affects the tumor immune microenvironment." (PMID 36845676, 2023). "Studies have found that serum GPX3 content can be used as a tumor marker." (PMID 36845676, 2023). "Accordingly, GPX3 is required for the tumor-polarized immunosuppressive function of AT2 cells." (PMID 38021154, 2023). "Additionally, several other studies have provided evidence that in tumor tissues and cancer cell lines, GPX3 expression is suppressed or completely blocked due to promoter hypermethylation or gene deletion." (PMID 36552527, 2022). "Studies have founded that GPX3 played a dual role in tumor development." (PMID 35978348, 2022). "HPRT1 reference gene findings were compared with those of the GPX3 gene, which exhibited little variation in both normal and tumor samples examined and is thus deemed a reliable and stable reference gene for RT-PCR (forward 5′-GGAAAGGGTGTT TATTCCTCA-3′, reverse 5′-TCCCAGGTCAGC AAAGAA-3′)." (PMID 35069731, 2022). "GPX3 was considered as a novel tumor suppressor which is downregulated in several types of cancer." (PMID 35712475, 2022). "GPX3 is a tumour suppressor gene and the main antioxidant enzyme in plasma." (PMID 36105798, 2022). "Finally, the expression of GPX3 in the transplanted tumor was significantly reduced by Western blot analysis." (PMID 35340708, 2022). "GPX3 has been proved to have a significant tumor-suppressive effect in various cancers." (PMID 36552219, 2022). "In addition, qRT-PCR detection data showed that the expression level of circ_0078767 and GPX3 was significantly decreased in the transplanted tumor with circ_0078767 knockdown, while the level of miR-665 was significantly increased." (PMID 35340708, 2022). "GPX3 is considered an antioxidant protein and a possible tumor suppressor gene." (PMID 35326089, 2022). "In contrast, GPX3 inhibits tumor progression in some tumors." (PMID 34926458, 2021). "Recent studies have elaborated on the tumor suppressor mechanism of the GPX3 gene." (PMID 33706760, 2021). "Among the glutathione peroxidases, GPx3 is the only one clearly acting as a tumor suppressor." (PMID 32426284, 2020). "Although a loss in GPx3 expression is associated with several tumor types, reports also demonstrate that GPx3 expression is increased in some cancer cells and may aid in tumor progression." (PMID 32781581, 2020). "GPx3 is well known for its roles in tumor suppression, and increased GPx3 expression may also play a protective role in cardiomyocytes by ROS detoxification." (PMID 33322741, 2020). "Based on the expanded correlation analysis results, we found that ACOX1, ALDH2, FUT6, and LRRC19 have a high association with GPX3 and DIO1 in the TCGA database, whether it is only tumor samples or “tumor samples + normal samples”." (PMID 32316597, 2020). "Low tumor GPx3 expression can also predict patient outcomes." (PMID 32781581, 2020). "Glutathione peroxidase 3 (GPX3), as a tumor suppressor, was suppressed in two tumors, could promote tumorigenesis." (PMID 32127786, 2020). "Hence the role of GPX3 in tumor progression is controversial and further mechanistic studies are needed to achieve specific targeting." (PMID 33050144, 2020). "It has been reported that GPX3 can act both as a tumor suppressor and a pro-survival protein." (PMID 33050144, 2020).
tumor (continued). "Tumor suppressor functions of GPx3 have also been identified." (PMID 32414091, 2020). "In addition to summarizing the biochemical function, regulation, and disease associations of GPx3, we specifically discuss the role and regulation of systemic and tumor cell expressed GPx3 in cancer." (PMID 32781581, 2020). "Moreover, it suggests that increased extracellular GPx3 activity confers survival advantages to tumor cells when exposed to exogenous insults, such as chemotherapeutic agents." (PMID 32781581, 2020). "Lower levels of plasma GPx3 were predictive of tumor progression and tumor recurrence." (PMID 32481552, 2020). "GPX3 was reported to act as a tumor suppressor in human cancer." (PMID 32782436, 2020). "This shows how GPx3 distribute throughout the lung tissue and the blood of patients, which implies this molecule might serve as tumor suppressor." (PMID 30260967, 2018). "Since GPx3 is highly expressed in healthy tissues, this suggests it may exhibit tumor suppressive activity." (PMID 28837649, 2017). "Interestingly, GPX3 expression was higher in clear cell epithelial ovarian carcinoma tissue compared to healthy control, suggesting a tumor-specific activity of GPX3." (PMID 27489351, 2016). "GPX3 tumor specific methylation may serve as a biomarker for early detection and prognosis prediction of ccRCC." (PMID 25970749, 2015). "We examined GPX3 protein expression in 54 ccRCCs and paired adjacent non-tumor tissues." (PMID 25970749, 2015). "Plasma GPX3 is mainly derived from kidney; however, in our study we found that expression of GPX3 was significantly downregulated in primary renal tumors compared with their adjacent non-tumor tissues (p < 0.0001)." (PMID 25970749, 2015). "GPX3 has been identified as a tumor suppressor in many cancers." (PMID 25970749, 2015). "In addition to indicating the clinical significance of GPx3, we also illustrated that over-expression of GPx3 in HCC cells significantly suppressed tumor proliferation and invasiveness in vitro and in vivo." (PMID 25333265, 2014). "Further research is required to understand whether there are other potential mechanisms involved in the tumor suppressive activity of GPx3." (PMID 25333265, 2014). "Moreover, we discovered the potential mechanism of GPx3 that suppressed invasiveness of tumor by inhibition of EMT through the Erk-NFκB-SIP1 signaling pathway." (PMID 25333265, 2014). "IHC staining also confirmed that lower expression of GPx3 was detected within tumor tissues." (PMID 25333265, 2014). "Tumor suppressive activity of GPx3 was mediated through Erk-NFκB-SIP1 pathway." (PMID 25333265, 2014). "The results showed that over-expression of GPx3 suppressed tumor invasiveness in vivo." (PMID 25333265, 2014). "It indicated that tumor suppressive activity of GPx3 through down-regulation of c-Met may be cell-type-specific." (PMID 25333265, 2014). "GPx3 could be delivered by hiPSC-MSCs into the tumor and exhibited tumor suppressive activity in vivo." (PMID 25333265, 2014). "It implied that down-regulation of GPx3 may not only be involved in tumor progression, but also tumor development or carcinogenesis." (PMID 25333265, 2014). "As such, we have shown that Gpx-3 serves as a tumor suppressor in the AOM/DSS model of CAC." (PMID 23861820, 2013). "Since GPX3 has been suggested to exhibit tumor suppressor activity, that could regulate the transcription of the oncogene, Met, we estimated the correlation of the expression between Met and Gpx3 by employing a real time RT-PCR expression study." (PMID 21106063, 2010). "The expression of the Met oncogene was slightly upregulated in EACs that showed loss of expression of Gpx3, but no tumor suppressor activity of Gpx3/GPX3 was detected." (PMID 21106063, 2010). "Hence, GPX3 may be involved in cancer by regulating the levels of ROS and may affect tumor progression by acting as a potent inhibitor of cancer development and progression." (PMID 38322113, 2024).
tumor (continued). "Therefore, tumor immune infiltration was probably responsible for GPX3-mediated GC." (PMID 37790850, 2023). "Thus, we analyzed the relationship between GPX3 and the tumor immune microenvironment (TIME)." (PMID 36845676, 2023). "In conclusion, DUBR/miR-502-3p/GPX3 may be a potential regulatory pathway for normal gastric epithelium mucosa transforms into GC and tumor progression, which activates at different stages of tumor development to inhibit or promote cancer." (PMID 37790850, 2023). "In cancer, GPX1 and GPX3 are tumor suppressors, while GPX2 may have dual roles in tumorigenesis." (PMID 36443446, 2022). "However, other studies found that GPX3 over-expression can promote tumor progression." (PMID 35978348, 2022). "As a tumor suppressor gene, GPX3 may be involved in the occurrence of a variety of cancer diseases." (PMID 35340708, 2022). "Thus, GPX3 functions as a tumor suppressor in an overwhelming majority of studies, and its overexpression, isolated or in combination with other components of the antioxidant system, is very promising for the suppression of endogenous or exogenous oxidative stress." (PMID 36552527, 2022). "In addition, the presence of GPX3 helps eliminate inflammation in the tumor microenvironment." (PMID 36552219, 2022). "Therefore, the potential of GPx3 as a tumor marker has been widely suggested." (PMID 33255360, 2020). "The exact mechanism of GPX3 loss is not known but might be associated with enhanced utilization of selenium and glutathione by tumor cells." (PMID 33050144, 2020). "This suggests that GPx3 might inhibit tumor progression by regulating the redox balance." (PMID 30260967, 2018). "Therefore, to examine whether GPx3 suppresses tumor growth, we generated H1975 cells overexpressing GPx3 and knocked down GPx3 expression in A549 cells using shRNA." (PMID 30260967, 2018). "Thus, GPx3 exerts tumor suppressor activity by directly or indirectly regulating cell growth and proliferation via an as yet unknown mechanism(s)." (PMID 30260967, 2018). "It implied that GPx3 could be successfully delivered by hiPSC-MSCs into tumor tissues." (PMID 25333265, 2014). "Immunohistochemical validation confirmed higher expression of key TELscore genes, including GPX3 and SEZ6L2, in tumor tissues compared to adjacent normal mucosa." (PMID 40492114, 2025). "The overexpression of GPX3 and JUN demonstrates significant tumor-suppressive activity, highlighting their potential as effective therapeutic targets in combating TC." (PMID 40092686, 2025). "Our study identified and validated the roles of GPX3 and JUN as tumor suppressors in the progression and metastasis of TC through various analytical methods." (PMID 40092686, 2025). "GPX3, the only extracellular isoform within the GPX family, functions as a tumor suppressor in the context of inflammatory colon carcinogenesis, likely through its ability to reduce ROS and mitigate DNA damage." (PMID 41300456, 2025). "The results showed that GPX3 and DOCK4 expression was significantly upregulated in normal cell lines, while LDHA expression was significantly upregulated in tumor cell lines." (PMID 38213730, 2024). "In all tumor tissues, TAMs replaced resident populations such as lung alveolar macrophages, prostate CTRB1+ macrophages, and renal GPX3+ macrophages." (PMID 38424167, 2024). "A total of 182 tumor tissues of EC and 286 normal tissues were retrieved from GEPIA to analyze the differential expression of GPx3." (PMID 38732573, 2024). "Patients that died over the course of the follow-up were older at time of diagnosis, more frequently post-menopausal, had larger tumours, more lymph nodes involved, lower serum Se and SELENOP concentrations and a lower serum GPx3 activity." (PMID 37741974, 2023). "The results demonstrated that NOS3 and TCIRG1 were highly expressed in tumor cells and samples compared to normal cells and tissues, while GPX3 and DUSP1 were expressed at low levels in tumor cells and samples." (PMID 37124616, 2023).
tumor (continued). "This analysis was performed using specific marker genes: GPX3 and ALDOB for proximal tubular cells and VIM, KRT18, NDUFA4L2, and NNMT for tumor cells." (PMID 37533434, 2023). "Another investigation confirmed that downregulation of GPX3 expression led to increased H2O2 levels in TME and promoted tumor malignancy." (PMID 37664836, 2023). "To further analyze the prognostic value of CALB2 and GPX3 in pan-cancer, we compared the expression levels of CALB2 and GPX3 in 32 tumor tissues and paraneoplastic tissues from TCGA and GTEx data." (PMID 37664836, 2023). "Additionally, catalase (CAT) and glutathione peroxidase 3 and 4 (GPX3 and 4) in shEPOR tumors were 3.5, 5, and 3.6 times lower than those in shSCR tumors (p<0.001), implying that the proportion of shEPOR A549 cancer cells in the tumor biopsies respire less than shSCR A549 cancer cells." (PMID 36052260, 2022). "Downregulation of GPX3 happened in PvsN analyses, leading to ascending of H2O2 level, which is positively correlated with tumor progression." (PMID 34249670, 2021). "All 3 oncogenes in 50 CRCs, except for MYC in one tumor and CDK4 in three tumors, were upregulated and 3 normal colonic physiological genes were downregulated, except for CD177 in one tumor, AQP8 in two tumors and GPX3 in three tumors." (PMID 31409279, 2019). "GPX3 expression is selenium dependent, since the existence of an opal stop codon in the mid section of the GPX3 open reading frame, and thus selenium supplements in cancer treatment may augment expression of GPX3 and could hold promise in suppressing tumor growth." (PMID 25970749, 2015). "We further examined GPX3 methylation status in primary RCC samples and their adjacent non-tumor tissues." (PMID 25970749, 2015). "We used methylation specific PCR (MSP) analysis to study DNA methylation status of EPB41L3, GPX3, and COL14A1 genes in tumor and paired surrounding normal tissue from 42 ESCC patients." (PMID 25050929, 2014). "The MSP analysis revealed that the methylation frequencies of EPB41L3, GPX3, and COL14A1 in ESCC tumor samples were 59.5%, 54.8%, and 45.2%, respectively." (PMID 25050929, 2014). "The methylation frequency of EPB41L3, GPX3, and COL14A1 were higher in tumor tissues than in normal surrounding tissues (P<0.017)." (PMID 25050929, 2014). "The higher methylation frequency of GPX3 and COL14A1 were correlated with advanced pN tumor stage (P = 0.001 and P<0.001)." (PMID 25050929, 2014). "We then focused on 3 aberrant DNA methylation genes—EPB41L3, GPX3, and COL14A1, with validation analysis using additional ESCC tumor tissues and adjacent normal tissues." (PMID 25050929, 2014). "Additionally, TELscore signature genes such as GPX3 and SEZ6L2 were highly expressed in tumor tissues compared to adjacent normal tissues." (PMID 40492114, 2025). "While the tumor-suppressive roles of TIAM1 and RAP1GAP have been previously established, our findings reveal that the overexpression of GPX3 and JUN significantly impairs the proliferative and migratory capacities of TC cells, underscoring their potential as therapeutic targets." (PMID 40092686, 2025). "Notably, we identify ANGPT2, PCSK1N, and GPX3 as key subtype-specific biomarkers, with ANGPT2 driving tumor progression in C1 and emerging as a potential therapeutic target." (PMID 41400463, 2025). "In the univariate analysis, early stage, no residual tumor after primary cytoreductive surgery and high expression of GPX3 were related to a better prognosis for OCCC patients (p = 0.010, 0.013, 0.021, respectively)." (PMID 37525249, 2023). "For example, GPX3, VIM, and IGFBP3 are known to be important markers in clear cell RCC,31,32,33 but much less is known about their patterns of spatial expression within the tumor." (PMID 37426750, 2023). "Consistent with our findings, previous studies showed that patients with recurrent HCC after tumor resection or after liver transplantation had lower plasma GPx3 levels than those in patients without HCC recurrence." (PMID 34836325, 2021).
tumor (continued). "The TXNRD1, GPX1, and GPX2 genes may exert dual effects in tumor mutagenesis and development, while the TXNRD1, GPX1, GPX2, and GPX3 genes were found to be related to drug sensitivity or the formation of drug resistance." (PMID 33706760, 2021). "We also analyzed the expression of GPX3 and DIO1 with the KIRC tumor stage." (PMID 32316597, 2020). "Glutathione peroxidase 3 (GPX3), a tumor suppressor gene that is located on chromosome 5q23, is the major antioxidant enzyme in plasma and plays an important role in detoxifying hydrogen peroxide and other oxygen-free radicals, protecting cell from oxidative stress-induced damage." (PMID 33392611, 2020). "Out of 54 ccRCC tumor tissues, GPX3 protein was negative in five (9.3%), weakly positive in 24 (44.4%), moderately positive in 17 (31.5%), and strongly positive in eight (14.8%)." (PMID 25970749, 2015). "GPX3 tumor specific methylation may serve as a potential biomarker for early detection and prognosis prediction of RCC, especially when GPX3 hypermethylation can be detected in patients’ serum and urine samples." (PMID 25970749, 2015). "To our knowledge, we report for the first time that GPX3 is frequently downregulated in renal tumors compared with their adjacent non-tumor tissues, indicating its role as a tumor suppressor." (PMID 25970749, 2015). "GPX3 methylation was further detected in 77.1% (162/210) of RCC tumors, but only 14.6% (7/48) of adjacent non-malignant renal tissues, indicating that GPX3 methylation is a tumor-specific event involved in tumorigenesis of RCC." (PMID 25970749, 2015). "In contrast, out of 54 adjacent non-tumor tissues, GPX3 protein was negative in 0, weakly positive in five (9.3%), moderately positive in 23 (42.6%), and strongly positive in 26 (48.1%)." (PMID 25970749, 2015). "Statistical analysis of the immunohistochemical results revealed that protein expression of GPX3 in ccRCC tumor tissues was significantly lower than in adjacent non-tumor tissues (p < 0.0001)." (PMID 25970749, 2015). "Firstly, we examined the clinical significance of GPx3 in HCC patients and found that lower expression of GPx3 in tumors could predict the advanced tumor stage and higher probability of tumor recurrence." (PMID 25333265, 2014). "Two of the tumor cell lines (NUT12 and NUT81) that displayed Gpx3 promoter biallelic hypermethylation were randomly selected for treatment with the demethylating agent 5-aza-2 ́-deoxy-cy-tidine (5Aza-dC) in combination with the histone deacetylace inhibitor, trichostatin A (TSA)." (PMID 21106063, 2010). "Regardless of tumor grade, the expression of GPX3 was low in all tumors, whereas the benign endometrial tissues exhibited a relatively high expression." (PMID 21106063, 2010). "To investigate whether Gpx3/GPX3 regulates the expression of Met/MET in the rat EAC and human tumor material, we performed qPCR on Met as well." (PMID 21106063, 2010). "Two of the tumor cell lines, NUT12 and NUT81, that displayed biallelic hypermethylation of the Gpx3 promoter, were selected for treatment with the demethylating agent 5-aza-2 ́-deoxy-cy-tidine (5Aza-dC) in combination with the histone deacetylace inhibitor, trichostatin A (TSA)." (PMID 21106063, 2010). "As the BDII rat strain did not exhibit a deletion in the region including Gpx3 most probably the deletion is an event that has occurred during the tumor development." (PMID 21106063, 2010). "GPX3 may play a role in resistance to platinum agents, and while it is not clear how, tumor‐induced downregulation could somehow be involved." (PMID 35906899, 2023). "Accumulating studies indicated that tumor development was closely related to metabolic and signaling pathways in the organism, we extracted 172 metabolic and signaling-related pathways in the organism among KEGG pathways and calculated their correlations with CALB2 and GPX3." (PMID 37664836, 2023).